IL6 (interleukin 6)
Diseases named in the same sentence as IL6 in open-access papers (continued):
Sharing a sentence is not in itself a finding about the gene and the disease.
rheumatoid arthritis (continued). "Tanshinones isolated from Danshen were able to ameliorate peroxidative damage, adjust the level of serum superoxide dismutase (SOD) and malonaldehyde (MDA), and inhibit the secretion of IL-6 and TNF-α, thus attenuating rheumatoid arthritis (RA)." (PMID 38542838, 2024). "As well as inflammatory related diseases such as “Rheumatoid arthritis” (FDR = 1.6x10−09) with MMP1/3 and IL6." (PMID 37962736, 2024). "IL-6 and TNF-α are well known to be involved in rheumatoid arthritis, with IL-6 promoting joint inflammation and destruction through cell signaling, and TNF-α initiating an inflammatory response leading to joint swelling and bone destruction." (PMID 39337919, 2024). "In general, in patients with rheumatoid arthritis who have experienced primary failure to an anti-TNF-alpha drug, switching to a different therapeutic target (IL-6, CTLA-4, JAK) is postulated to be more effective than cycling to another anti-TNF-alfa." (PMID 39685848, 2024). "Although the roles of IL-6 and TNF-α in rheumatoid arthritis and in chronic chikungunya arthritis are well established, we saw a reduction during the acute phase." (PMID 38235127, 2023). "The clinical course of rheumatoid arthritis has been transformed by targeted therapies, including those aimed at TNF, IL-6, B cells, T cell co-stimulation and the JAK–STAT pathway." (PMID 37938773, 2023). "Rheumatoid arthritis (RA) is an autoimmune disease that primarily affects the synovial membranes and causes excessive production of pro-inflammatory cytokines and chemokines, such as tumor necrosis factor (TNF)-α and interleukin (IL)-6 in synovial membranes." (PMID 37298711, 2023). "In fibroblast-like synoviocytes from rheumatoid arthritis patients, silencing SOX5 decreased IL-6 expression and reduced MMP-1,-2, and -9." (PMID 36835058, 2023). "For example, in the context of rheumatoid arthritis, HIF-1α was shown to directly interfere with the production of TNF-α, IL-1β, IL-6 and IL-8." (PMID 38273861, 2023). "Another recent study showed that Baricitinib, a JAK inhibitor blocking central inflammatory signaling pathways decreases systemic inflammation biomarkers, such as IL-6, CRP, as well as adiponectin, in rheumatoid arthritis patients." (PMID 36774444, 2023). "LXA4 inhibited synoviocyte proliferation and also decreased the levels of IL-6, IL-1β, and TNF-α in rheumatoid arthritis." (PMID 37388729, 2023). "Three of the most essential aspects in the onset and regression of rheumatoid arthritis are TNF- α, IL-1 β, and IL-6." (PMID 37520245, 2023). "Therefore, to assess whether the defect in LXR signalling is because of a failure of oxysterol production or signalling, we performed lipidomics on BMDMs treated with a cocktail of inflammatory cytokines associated with rheumatoid arthritis (TNF, GM‐CSF, IL‐1β and IL‐6)." (PMID 37091327, 2023). "Notably, high CTRP1 and CTRP6 serum levels are also associated with increased TNF-α, IL-1β, and IL-6 blood concentrations, and CTRP1 and CTRP6 serum levels are increased in patients suffering from chronic inflammatory diseases, such as rheumatoid arthritis and Kawasaki disease." (PMID 37047812, 2023). "IL-1β, IL-6, IL-8, and TNF-α are involved in the pathogenesis of many inflammatory diseases including rheumatoid arthritis, psoriatic arthritis, and IBD." (PMID 36505430, 2022). "The results of KEGG pathway analysis revealed that IL-6 is mainly involved in the Jak-STAT signaling pathway and rheumatoid arthritis." (PMID 34986839, 2022). "We have reported that activation of Interleukin (IL)-6 signaling contributes to chondrogenic differentiation of MSCs in vitro and partial repair of damaged articular cartilage in antigen-induced arthritis rats as a model of rheumatoid arthritis (RA) in vivo." (PMID 36548354, 2022). "Cytokines produced from many synovial cell groups are the core of the pathogenesis of rheumatoid arthritis, including a variety of cytokines TNF-α, IL-1 family, and IL-6." (PMID 35600883, 2022).
rheumatoid arthritis (continued). "Excess IL-6 levels also stimulate angiogenesis and increased vascular permeability via increased VEGF levels, as observed in rheumatoid arthritis." (PMID 35392889, 2022). "For instance, gallic acid suppresses the levels of cytokines IL-1 and IL-6, chemokines MCP-1 and MCP-3, cyclooxygenase-2 (COX-2), and matrix metalloproteinase-9 (MMP-9) in fibroblast-like synoviocytes in rheumatoid arthritis." (PMID 36235070, 2022). "Extract 3 attenuates the severity, pathological changes, and release of cytokines (IL-6 and HIF-1α) during rheumatoid arthritis progression by regulating the PI3K/Akt and HIF-1 pathways." (PMID 36330088, 2022). "As we know, a clinically tested blocking antibody against IL-6 is available, and the Food and Drug Administration (FDA) approved it for rheumatoid arthritis and acute cytokine release syndrome treatment." (PMID 36544757, 2022). "Moreover, knocking out IKKε can reduce the expression of NF-κB, TNF-β, IL-1ε, and IL-6, unveiling a new direction for treating rheumatoid arthritis (RA)." (PMID 35729649, 2022). "Resveratrol shows its anti-rheumatoid arthritis properties with reduced RA patients’ swelling, tenderness, and disease activity by lowering the biochemical indicators of inflammation like MMP-3, IL-6, ESR, C-reactive protein, and undercarboxylated osteocalcin." (PMID 35237163, 2022). "It is well known that IL-6 and TNF-α are confirmed to mediate many chronic inflammatory diseases, especially rheumatoid arthritis." (PMID 36578485, 2022). "The therapeutic blockage of IL-6 with Tocilizumab (TCZ) alters PLT and the phenotype and function of monocytes in rheumatoid arthritis (RA)." (PMID 35628558, 2022). "Among these potential therapeutic targets, the establishment of anti-IL-6 and TNF-α antibodies, as well as Janus kinase (JAK) inhibitor therapies for rheumatoid arthritis, have been the most successful." (PMID 35563063, 2022). "It was suggested that IgA autoantibodies induce release of IL6 and IL8 by immune cells, as well as osteoclasts, which enhances bone resorption by osteoclasts, possibly reflecting enhanced rheumatoid arthritis pathogenesis." (PMID 36232432, 2022). "In rheumatoid arthritis (RA) model, BAFF promoted B-cell survival and also secretion of pro-inflammatory factors IL-6 and IL-8 in mice, consistent with the result in synovial fibroblasts co-cultured with INF-γ." (PMID 35320937, 2022). "It is well accepted that macrophages play an essential role in the pathogenesis of inflammatory disease rheumatoid arthritis (RA) by producing pro-inflammatory cytokines like TNF-α, IL-1β, IL-6 that can drive osteoclastogenesis and bone destruction." (PMID 34421899, 2021). "In rheumatoid arthritis, CYR61 was found to be overexpressed in the synovial tissue of patients and was able to induce the expression of IL-6, CCL20, IL-1β, and MMP-3 in cultured fibroblast-like synoviocytes from patients." (PMID 33542676, 2021). "A clinical trial of Sirukumab, a human monoclonal antibody against IL-6, in severe asthma was withdrawn after FDA had disapproved Sirukumab (NCT02794519) for treatment of rheumatoid arthritis, due to increased number of deaths and malignancies among patients." (PMID 34084159, 2021). "The drug significantly regulates the cytokines IFN-γ, IL6, IL17F, and IL22 s in peripheral blood mononuclear cells of rheumatoid arthritis subjects." (PMID 34064039, 2021). "Fortunately, IL-6 and TNF-α have recently been shown to regulate miR-34a transcription and participate in rheumatoid arthritis." (PMID 34504639, 2021). "Similar studies have been conducted in other immunological diseases; in rheumatoid arthritis, ADA treatment resulted in reductions in plasma levels of chemerin, correlated with decreases in IL-6 and macrophage migration inhibitory factor concentrations." (PMID 34640632, 2021).
rheumatoid arthritis (continued). "Elevated IL-17B levels have been reported in the synovial tissues of rheumatoid arthritis patients, which can promote TNF-α-induced G-CSF and IL-6 expression in fibroblasts." (PMID 33545363, 2021). "IL-6 and TNF-α have important roles in the early- and late-stage pathogenesis of rheumatoid arthritis." (PMID 34064515, 2021). "The new formulation developed for SSZ as PLGA MPs prepared with α-tocopherol produced a decrease in IL-1, IL-6 and TNF-α levels thereby resulting in an adequate delivery system for the treatment of chronic inflammatory diseases such as rheumatoid arthritis." (PMID 34202859, 2021). "TwHF significantly inhibits inflammatory molecules including IL-6, TNF-α, and COX-2 which are up-regulated in the development and progression of rheumatoid arthritis." (PMID 34108880, 2021). "IL-6 is a proinflammatory cytokine that plays a crucial role in several autoimmune diseases including EAE and rheumatoid arthritis." (PMID 34395636, 2021). "CDK4/6 inhibitor palbociclib inhibited the proliferative phase of rheumatoid arthritis in an animal model, especially when combined with TNF-a or IL-6 blockers." (PMID 34198899, 2021). "Moreover, DHA derivative DC32 inhibits the immune system imbalance and lymphocytic infiltration in synovitis of rheumatoid arthritis (RA) by restoring Treg/Th17 balance through inhibition of IL-6." (PMID 34483908, 2021). "Baricitinib, a JAK inhibitor blocking central inflammatory signaling pathways, was recently shown to decrease systemic inflammation biomarkers, such as IL-6, CRP, as well as adiponectin, in rheumatoid arthritis patients." (PMID 33499006, 2021). "Circulating chemerin levels are increased in various inflammatory diseases such as rheumatoid arthritis and correlate to disease activity and to several circulating pro-inflammatory markers, such as TNF-α, IL-6, and CRP." (PMID 34639186, 2021). "For rheumatoid arthritis (RA), three JAK inhibitors and a range of bDMARDs are approved, including those targeting TNFα, IL-6, IL-1β, B cells (CD20), and T cells (CD80/CD86)." (PMID 34290741, 2021). "On the other hand, it has been reported that TNF-α and IL-6 upregulate the expression of the chemokine receptors CCR5 and CXCR3 on Vδ2 T cells in patients suffering from rheumatoid arthritis." (PMID 34900753, 2021). "Interleukin-6 (IL-6) is a key cytokine in rheumatoid arthritis (RA)." (PMID 34112702, 2021). "IAld I3AA inhibited the expression of IL1b and IL6 in an AhR dependent manner, whereas I3AA showed AhR-independent anti-angiogenic activity in cell-based models of rheumatoid arthritis." (PMID 34639632, 2021). "IL-6, TNF-α and LPS stimulate the expression of E2F2 in rheumatoid arthritis synovial fibroblasts via NF-κΒ, ERK and STAT3 pathway." (PMID 33530456, 2021). "Besides, TNFR2 upregulation in rat and human BM-MSCs effectively increased their therapeutic potential in cardiac ischemia and inflammatory disorders like rheumatoid arthritis (RA), which was accompanied by decreased IL-6, IL-1β, and TNFα secretion." (PMID 33344453, 2020). "Enhanced IL-6 trans-signaling is observed in chronic obstructive pulmonary disease (COPD), rheumatoid arthritis, inflammatory bowel disease, and other autoimmune diseases." (PMID 33284859, 2020). "In rheumatoid arthritis, TNF-α, Interleukin (IL)-1, IL-6, and IL-17 produced by synovial macrophages and T cells act on osteoblasts to promote RANKL expression." (PMID 32708317, 2020). "IL-6 activates the immune system, favoring the inflammatory response, and in the joint, IL-6 expression correlates positively with the intensity of the lesions observed in aseptic joint diseases, such as rheumatoid arthritis (RA)." (PMID 33202791, 2020). "Several inflammatory cytokines, such as TNFα, IL-1, IL-6, IL-17, and receptor activator of nuclear factor-kappa B ligand (RANKL), play an important role in the pathogenesis of rheumatoid arthritis." (PMID 32079226, 2020).
rheumatoid arthritis (continued). "It has been shown that the methotrexate treatment reduces the TNFα, IL1β, and IL6 production and increases the IL10 expression in the synovial tissue of rheumatoid arthritis patients." (PMID 31958219, 2020). "TNF-α significantly induced IL-33 mRNA expression and protein synthesis, and overexpression of IL-33 significantly increased TNF-α-induced IL-6, IL-8, and matrix metalloprotease (MMP)-3 in rheumatoid arthritis synovial fibroblast." (PMID 33490289, 2020). "Dysregulation of IL-6 has been implicated in the onset or development of several diseases, particularly inflammatory disorders such as rheumatoid arthritis (RA), whereby elevated levels of IL-6 in serum, synovial fluid, and various tissues have correlated with increased RA disease activity." (PMID 33081825, 2020). "HIF-1α acts as a key regulator during inflammation, increasing pro-inflammatory cytokines (e.g., TNF-α, IL-1β, IL-6, and IL-8), matrix metalloproteinases (e.g., MMP-1, MMP-3, and MMP-9), and pathways of glucose metabolism in rheumatoid arthritis (RA)." (PMID 33374961, 2020). "Both the classical mIL-6R-mediated signaling pathway and the sIL-6R-mediated IL-6 trans-signaling pathway lead to the activation of the JAK/STAT signaling pathway, a major therapeutic target for immunological diseases including rheumatoid arthritis." (PMID 32932973, 2020). "Serum and synovial fluid of patients with rheumatoid arthritis have high amounts of proinflammatory cytokines such as TNF-α, IL-1β, and IL-6." (PMID 32708317, 2020). "Transfection of miR-20a mimic reduced the release of IL-6, CXCL10, and IL-1β, as well as TNF-α by rheumatoid arthritis fibroblast-like synoviocytes." (PMID 33584204, 2020). "Although in these cases there are not as many optical sensors as for miRNA and C-reactive protein, the rheumatoid factor (RF) and the ACPA are widely mentioned in rheumatoid arthritis literature while histidine and IL-6 are the other two RA biomarkers covered in this section." (PMID 33158306, 2020). "In patients with rheumatoid arthritis, vitamin B6 supplementation improved pro‐inflammatory responses by suppressing TNF‐α and IL‐6 levels." (PMID 32967056, 2020). "Extending these studies to primary cells, these lead compounds also reduced IL-6 and CXCL8 production by TNF stimulated fibroblast-like synoviocytes (FLS) from rheumatoid arthritis (RA) patients." (PMID 33390996, 2020). "Drugs that inhibit IL-6, IL-6R and JAK signaling (activated by IL-6 family members) are FDA-approved for the treatment of rheumatoid arthritis and other inflammatory conditions and are currently being evaluated in patients with COVID-19." (PMID 32629875, 2020). "GA suppresses the expression of several proinflammatory mediators, such as IL-6, IL-1β, CCL2 and CCL7, in fibroblast-like synoviocytes from rheumatoid arthritis patients." (PMID 31026283, 2019). "Polyphenols reduce rheumatoid arthritis symptoms by regulating an extensive collection of RA-related molecules, including MAPK, IL-1β, IL-6, TNF-α, NF-κB, JNK, ERK1/2, AP-1 and COX-2." (PMID 31013659, 2019). "Many cytokine inhibitors, including those targeting IL‐1β, IL‐6, and TNF‐α, have been approved for the treatment of inflammatory diseases, such as bone destruction and rheumatoid arthritis." (PMID 30414292, 2019). "Gold compounds decrease the expression of inflammatory cytokines (IL-1, IL-6 and TNF) in rheumatoid arthritis patients." (PMID 31308463, 2019). "In the bootstrap resampling, we selected several important rheumatoid arthritis genes such as MMP genes (MMP1, MMP3), CCL genes (CCL3, CCL4, and CCL26), and IL genes (IL6, IL8, IL19, and IL24)." (PMID 31371761, 2019). "For instance, a study detected US synovitis of wrist joints in 50 early rheumatoid arthritis patients, and disclosed PD-US synovitis showed positive correlation with TNF-α, IL-6, and angiopoietin-1 and -2 levels." (PMID 31778437, 2019).
rheumatoid arthritis (continued). "In another study using a rheumatoid arthritis model of inflammation induced by LPS in vitro, hyperoside has demonstrated a significant (concentration-dependent) effect on inhibition of TNF-α, IL6 and IL-1β." (PMID 31405193, 2019). "IL-6 produced by human fibroblast-like synoviocytes (HFLS) promotes rheumatoid arthritis (RA), while lncRNA DILC regulates liver cancer stem cells by inhibiting IL-6." (PMID 30944206, 2019). "IL-6, which is rheumatoid arthritis, systemic lupus erythematosus biomarker, was detected using Poly-HRP labeled anti-IL-6 antibodies, Gold compact disc, and an 8-electrode array system." (PMID 31324020, 2019). "In patients with rheumatoid arthritis, numerous cytokines such as TNF-α, IL-1β, IL-6, IL-8, and IFN-γ are produced and are functionally active in synovial tissues, leading to cytokine-driven joint inflammation and damage." (PMID 31780866, 2019). "It has been reported that inflammatory cytokines such as IL-1β, IL-6 and TNF-α express in rheumatoid arthritis (RA) and induces osteoclastogenesis via increasing the expression of RANKL." (PMID 31763378, 2019). "During rheumatoid arthritis, neutrophils accumulate and destroy the synovial tissue in response to TNF-α and IL-6." (PMID 31362372, 2019). "Li and coworkers demonstrated that hesperidin decreased the production of IL-1β, IL-6, and TNF-α in a rat model of rheumatoid arthritis." (PMID 30347737, 2018). "Der therapeutische Index bei rheumatoider Arthritis (RA) lässt sich möglicherweise mit einer MTX-Therapie verbessern, die auf dem zirkadianen Rhythmus von IL-6 basiert." (PMID 27900440, 2018). "Specifically, in rheumatoid arthritis, naïve helper T-cells are considered to differentiate into Th17 cells by the action of molecules such as transforming growth factor (TGF)-β, IL-6, and IL-23." (PMID 29389956, 2018). "The collagen-induced arthritis mouse model is known as a human rheumatoid arthritis model and is reported to exhibit mRNA increases in TNF-α, IL-1β, IL-6, and IL-18 during the progression of arthritis." (PMID 29389956, 2018). "In many inflammatory disorders, most notably, rheumatoid arthritis, TNF stands atop a cytokine hierarchy that can include IL6 (refs 34, 35)." (PMID 28548091, 2017). "Proinflammatory cytokines such as IL-1β, IL-6, and TNF-α are not only key mediators in rheumatoid arthritis, they are also present in the joint in human and experimental OA." (PMID 29163027, 2017). "Ca-gluconate has been shown to reduce expression of pro-inflammatory cytokines IL-6 and TNF-α, as well as myeloperoxidase levels in both burn and rheumatoid arthritis mouse models." (PMID 28604843, 2017). "Rheumatoid arthritis (RA) is a chronic inflammatory disease characterized by the destruction of articular cartilage and bone with elevated levels of proinflammatory cytokines, such as TNFα and IL-6, produced from the synovial tissue." (PMID 27123445, 2016). "IL-6 is essential for the up-regulation of HAMP upon inflammation and IL-6 blockade for the treatment of rheumatoid arthritis lowers both disease activity and circulating HAMP levels." (PMID 27557596, 2016). "Similarly Zavaleta-Muñiz and colleagues could not detect correlation between 174G/C and -572G/C IL6 promoter gene polymorphisms and rheumatoid arthritis which is a condition with chronic inflammation." (PMID 26714766, 2015). "Mechanistically, ciclamilast inhibited an increase in the expression level of IL-1β, IL-6, and TNF-α, leading to potential effects on both the acute and chronic phases in the treatment of rheumatoid arthritis." (PMID 26000303, 2015). "Significant examples are the elevated production of IFN-γ, IL-6 and IL-17 consequent to an estrogen deficit in menopausal osteoporosis or the action of TNF-α in secondary osteoporosis due to rheumatoid arthritis." (PMID 26449657, 2015). "Tocilizumab blocks IL-6 signaling and has been approved by the Food and Drug Administration (FDA) for use in selected patients with rheumatoid arthritis." (PMID 26640809, 2015).